NRAS (NRAS proto-oncogene, GTPase)
Diseases named in the same sentence as NRAS in open-access papers (continued):
Sharing a sentence is not in itself a finding about the gene and the disease.
melanoma (continued). "After BRAF mutations, NRAS mutations are the second most common oncogenic driver genetic mutations in melanoma." (PMID 36600247, 2023). "We aimed to evaluate the safety and efficacy of HL-085 in patients with advanced melanoma harboring NRAS mutations." (PMID 36600247, 2023). "In the smaller diagnosis cohort, one melanoma case had a NRAS Q61R variant and the other case of melanoma had a BRAF V600E variant." (PMID 36125633, 2023). "As this effect has yet to be confirmed in vivo, further research on such novel drug combinations is needed to develop an effective therapy against NRAS-mutated melanomas." (PMID 38067230, 2023). "The combinations of dabrafenib + trametinib, vemurafenib + cobimetinib, and encorafenib + binimetinib have demonstrated efficacy against melanomas with mutations in both the NRAS and BRAF genes, and are shown to improve therapy response and overall PFS." (PMID 37181747, 2023). "Altogether, we demonstrate that tumor-intrinsic features of NRAS-mutated melanoma cells are decisively controlled by the vascular route tumor cells take during organ colonization." (PMID 37179302, 2023). "BRAF and NRAS mutations in the MAPK signaling pathway are found in about half of all melanoma cases, resulting in constitutive activation of the MAPK pathway." (PMID 36747120, 2023). "NRAS mutation is frequently observed in several cancer types, including melanoma (15–20%), leukemia (10%), and occasionally other cancer types." (PMID 37083947, 2023). "The co-occurrence of BRAF or NRAS mutations with TERT promoter mutations was also prognostic for poor disease-free survival in multivariate analyses in primary melanoma." (PMID 37418389, 2023). "Fifty percent of NRAS-mutant melanomas have genetic aberrations in cell-cycle-associated genes providing a rationale for combining MEK inhibitors with CDK4/6 inhibitors." (PMID 37370834, 2023). "Mutations leading to activation of BRAF (BRAFV600 mutations) and NRAS occur in 50% and 15–20% of melanoma respectively." (PMID 36588164, 2023). "A retrospective multicenter analysis of 364 patients concluded that additional MEK inhibition to immune checkpoint inhibition has potential to increase survival of NRAS-mutated melanoma patients and improve clinical benefit." (PMID 37808191, 2023). "RAB27B depletion impaired the PM localization of NRAS in both NRAS-mutated leukemia and melanoma cells." (PMID 37317963, 2023). "Other genes and proteins, such as KRAS, NGFR (nerve growth factor receptor), and NRAS (neuroblastoma ras viral oncogene homolog), are also implicated in melanoma BM development." (PMID 37484759, 2023). "BRAF and MEK inhibitors do not appear to be a promising therapeutic regimen for the treatment of melanoma patients with NRAS-mutated metastatic melanoma when applied at the currently used doses for the treatment of BRAFV600E/K melanoma." (PMID 38067230, 2023). "In phase 2, binimetinib showed activity in patients with NRAS-mutated melanoma as a first-targeted therapy." (PMID 38067230, 2023). "MIRAT has been demonstrated to bind and stabilize cytoplasmic scaffold protein IQ motif containing GTPase activating protein 1 (IQGAP1) that positively regulates the MAPK pathway in NRAS mutated melanomas." (PMID 37325482, 2023). "This patient sample analysis is also in accordance with our finding that drug-induced MAPK-inhibition causes dose-dependent MALAT1-upregulation in NRAS-mutant melanoma." (PMID 37235843, 2023). "Recent findings show that the prevalence of ERBB4 mutations in melanoma is relatively low compared to other genetic alterations like BRAF or NRAS mutations." (PMID 37504268, 2023). "NRAS mutations in melanoma promote RAS-MEK signaling cascade by switching their signaling from BRAF to CRAF, facilitated by the disruption of the cAMP-PKA inhibitory pathway on CRAF activity." (PMID 38111008, 2023). "The coexistence of mutations in BRAF and NRAS genes as well as in TERT promoter are associated with poor disease-free survival in melanoma patients." (PMID 38033865, 2023).
melanoma (continued). "Benign melanocytic nevi harbour trunk nucleotide changes, such as BRAF and NRAS mutations, before progressing to melanoma and accumulate nucleotide changes in TERT promoter at the transition from benign nevus to melanoma in situ." (PMID 38033865, 2023). "Melanoma cells with NRAS mutations have elevated mitotic activity, causing thicker lesions and a higher rate of metastasis as a consequence of persistent NRAS signaling." (PMID 37083947, 2023). "BRAF mutated patients had significantly higher expression of APRIL/TNFSF13 and CXCL10 in comparison to BRAF wild-type patients, while NRAS wild-type patients had higher expression of TNFSF13 in comparison to patients with melanomas harboring NRAS mutations." (PMID 37435077, 2023). "BRAF mutations are prevalent in CLs derived from melanoma and colorectal cancers, and NRAS in melanoma, leukemia, bladder cancer, and lymphoma." (PMID 37830744, 2023). "On the other hand, BRAF and NRAS mutations are frequently encountered in dedifferentiated melanomas with conventional nodular or superficial spreading components." (PMID 37373134, 2023). "Limited treatment options are available for patients with NRAS-mutated melanoma, mainly consisting of participation in clinical trials like TIL therapy or fecal microbiota transplantation, as well as chemotherapy." (PMID 38067230, 2023). "Other NRAS mutations, such as G12S and G13D, have also been identified in melanoma, although they are less common." (PMID 37504268, 2023). "Amongst HRAS-mutant melanomas, 42% carried a co-altered NF1 mutation, significantly greater than in KRAS-/NRAS-mutant melanoma and other HRAS-mutant cancers (p<0.05)." (PMID 37503077, 2023). "Our study demonstrates that hepatic passaging of NRAS-mutated melanoma, WT31, shifts its typical metastatic propensity by regulation of tumor cell adhesion at the primary vascular site and adaptation to the metastatic site." (PMID 37179302, 2023). "As already seen in the normalized data, MALAT1 expression was significantly decreased in BRAF- and NRAS-mutated melanoma (13.5-fold, p < 0.001), LIHC (3.3-fold, p < 0.001) and LUSC (8.7-fold, p < 0.001), when compared to their corresponding healthy tissue." (PMID 37235843, 2023). "We identified NRAS Q61R/K/L mutations in 14 canine tumors, 57% (8/14) of which were hemangiosarcoma, 28% (4/14) malignant melanoma, 7% (1/14) plasma cell tumors and 7% (1/14) soft tissue sarcoma." (PMID 37414794, 2023). "Compound 68 showed higher potency against the melanoma cell lines that include B-RAF V600E mutation compared to melanoma cells possessing the NRAS mutation as well as normal epithelial skin cells." (PMID 35011562, 2022). "NRAS mutations occur in 15%‐25% of melanoma cases, most often in exons 2 (codon 12) and 3 (codon 61)." (PMID 34110110, 2022). "Similar results were obtained in PDX models of BRAF-V600E-mutant melanoma refractory to BRAFi/MEKi therapy which harbored mutations in NRAS and CDKN2A." (PMID 35565444, 2022). "Most specimens with NRAS mutations were from acute myeloid leukemia patients (approximately 38%), followed by malignant melanoma (21%) and lung adenocarcinoma (4%)." (PMID 35627184, 2022). "In this study, CTNNB1 mutations only occurred in BRAF or NRAS mutated melanomas, suggesting a cooperation between MAPK and Wnt/β-catenin signaling pathways." (PMID 36077603, 2022). "The host defense derived peptide was assessed in different model systems with increasing complexity employing the highly aggressive NRAS mutated melanoma metastases cell line MUG-Mel2." (PMID 36428530, 2022). "Hotspot mutations in the NRAS gene, especially codon Q61, less frequently G12 and G13, can be found in approximately 10–25% of melanomas." (PMID 35380338, 2022). "BRAF and NRAS are two major genes often mutated in human melanoma and are associated with melanoma initiation and progression." (PMID 36291794, 2022). "If more different kinds of melanoma cell lines with NRAS mutation can be used, this study will be enriched." (PMID 35310910, 2022).
melanoma (continued). "Activating mutations in KRAS, HRAS, and NRAS occur in over 30% of all cancers, with particular prevalence in pancreatic, melanoma, multiple myeloma, and colon cancers." (PMID 35923912, 2022). "Other melanoma mutations associated with the MAPK pathway take place within NRAS and KIT genes and account for 15–30% and 1–2% of cutaneous melanoma genetic alterations, respectively." (PMID 35158770, 2022). "Melanoma is an aggressive tumor characterized by mutations in the oncogenes BRAF or NRAS, resulting in the overactivation of the MAPK/ERK and PI3K/Akt pathways." (PMID 36060947, 2022). "For example, the MEK inhibitor binimetinib extends survival in melanoma patients with NRAS mutations and is a new treatment option for melanoma patients with NRAS mutations that have failed immunotherapy." (PMID 35310910, 2022). "NRAS mutations occurred in two melanomas, both in the presence of androgenetic alopecia and elastosis." (PMID 36064728, 2022). "The MEK inhibitor binimetinib has shown activity in this setting, with a response rate of 20% in a Phase II trial of 30 patients with NRAS-mutated melanoma." (PMID 35159047, 2022). "Expression of the gain of function mutation R264C cooperated with BRAF and NRAS oncogenes to reduce mitfa expression and led to an increase in melanoma proliferation in a zebrafish model system." (PMID 35368039, 2022). "Studies based on double-mutant engineered melanoma cells containing NRAS and BRAF activating mutations showed that the expression of the two genetic alterations can induce cell senescence because of an overactivation of the RAS/RAF/ERK pathway." (PMID 35580987, 2022). "The study investigates the sensitivity of the aggressive NRAS mutated melanoma MUG-Mel2 for treatment with antitumor peptide RDP22." (PMID 36428530, 2022). "Here we establish that functional differences underlie the enrichment of specific NRAS mutants in human melanoma." (PMID 35672316, 2022). "In BRAF- and NRAS-mutated melanoma, tumor proliferation and cell survival are substantially driven by increased activation of the MAPK pathway." (PMID 35380338, 2022). "Further understanding of the role of NRAS mutations in Indonesian melanoma cases will be crucial in developing new management strategies for melanoma patients with NRAS mutations." (PMID 34110110, 2022). "Melanoma is classified into several molecular subgroups based on genomic alterations, among which B-RAF and NRAS mutated melanomas are the most common." (PMID 35756619, 2022). "Some specific driver mutations have been described in multiple oncogenes including BRAF and NRAS that are mutated in 60–70% and 15–20% of melanoma, respectively." (PMID 36400750, 2022). "Due to a lack of specific NRAS-targeted therapeutics, MEK inhibitors are often used in NRAS-mutated melanomas which have failed therapy with immune checkpoint inhibitors [38••]." (PMID 35380338, 2022). "For example, epidermal growth factor receptor (EGFR) mutations and ALK rearrangements are usually indicative of a lung cancer origin (most CUP cases), while BRAF and NRAS mutations are associated with melanoma." (PMID 35225863, 2022). "The NRAS mutation is found in 15–20% of melanomas tested and is an inaccurate predictor of disease prognosis." (PMID 36232957, 2022). "NRAS‐mutant tumors are likely to act aggressively, especially in the early stages in the high‐risk melanoma population." (PMID 34110110, 2022). "NRAS mutations in exon 2 (codons 12 and 13) were detected in digital melanomas of the right forelimbs of two Golden Retrievers." (PMID 35202309, 2022). "Mechanistically, the authors found that in both BRAF and NRAS mutated melanomas, MEK inhibition increases MITF expression, which, in turn, upregulates the expression of PGC-1α." (PMID 36077374, 2022).
melanoma (continued). "By contrast, NRAS mutations or BRAF V600K or K601E mutations are more commonly associated with intermediate melanoma lesions, which had already accumulated other pathogenic mutations." (PMID 35159386, 2022). "Although activation of these molecules within the RAS pathway leads to the activation of ERK1/2, BRAF- and NRAS-mutated melanomas represent two different clinical and biochemical entities, as they exhibit different signaling patterns and biological responses." (PMID 36402789, 2022). "BRAF mutations occur in 60% while NRAS mutations occur in 20% of melanoma patients both causing constitutive activation of the MAPK pathway, thereby driving uncontrolled cell proliferation and increasing resistance to cell death." (PMID 35379799, 2022). "This is particularly evident in melanocytic lesions where common nevi and malignant melanomas harbor almost exclusively NRAS mutations while Spitz neoplasms HRAS mutations." (PMID 35457030, 2022). "The current treatments of melanoma patients with NRAS mutations are primarily focused on the use of MEK inhibitors to target key signal transduction pathways of the MAPK pathway." (PMID 36125617, 2022). "This highlights the need for any melanoma detection assay to include TERT promoter mutations in order to maximize detection rates in BRAF/NRAS WT patients." (PMID 35494035, 2022). "NRAS wildtype melanomas with NOTCH4-Mut were identified to be associated with prolonged overall survival (OS) in both the discovery (HR: 0.30, 95% CI: 0.11–0.83, P = 0.01) and validation cohorts(HR: 0.21, 95% CI: 0.07–0.68, P = 0.003)." (PMID 35967450, 2022). "They concluded that the presence of NRAS mutation in melanomas of the female urogenital tract makes NRAS an interesting therapeutic target for these patients in the advanced setting." (PMID 36407184, 2022). "Cutaneous melanoma ranks amongst the tumor types with the highest rate of oncogenic mutations in members of the RAS–ERK pathway: 15–20% of melanomas harbor mutant NRAS, whereas oncogenic BRAF appears in 50–60% of the cases." (PMID 36358912, 2022). "In melanoma samples, NRAS mutations co-occurred much less frequently with BRAF mutations than expected." (PMID 36275468, 2022). "Targeted therapies for NRAS-mutant melanoma have been hampered by the high number of NRAS mutations and no one is available at present." (PMID 36400750, 2022). "Ulixertinib (BVD-523) is a widely used ERK inhibitor for the treatment of NRAS-mutated melanoma and BRAF-mutated solid tumors." (PMID 36233210, 2022). "NRAS mutation is the second most common among melanoma patients, yielding a more aggressive phenotype than BRAF mutants." (PMID 35621952, 2022). "The use of MEK inhibitors in NRAS-mutated melanoma cells has been extensively studied, and more novel inhibition methods are needed." (PMID 35310910, 2022). "Inhibition of both MEK and autophagy resulted in tumor regression in patient-derived xenografts of NRAS-mutated melanoma." (PMID 35954441, 2022). "NRAS-mutated melanoma is distinct from BRAF-mutated melanoma in clinical presentation and prognostic features." (PMID 36402789, 2022). "Despite the fact that c-KIT mutation occurred at a lower incidence than BRAF and NRAS genes in most of the melanoma patients, it represented 36% of acral lentiginous melanomas in cutaneous melanoma." (PMID 35720122, 2022). "The ability to detect somatic TERT promoter mutations co-occurring with BRAF or NRAS mutations is also valuable given that a TERT-mutation positive genetic profile is associated with a worse prognosis for melanoma patients." (PMID 35494035, 2022). "Oncogenic NRAS mutations in GIMM exhibit its significance for systematic approaches to melanoma genesis and maintenance." (PMID 36551688, 2022).
melanoma (continued). "STK19 is frequently mutated in melanoma and the most-frequent mutation, D89N appears to act as a gain-of-function that amplifies NRAS downstream signaling, promoting melanocyte transformation in vitro and in vivo." (PMID 35234863, 2022). "Our in vitro tests demonstrated that blockade of the forward NCX effectively inhibited the growth of melanoma cells which have either BRAF or NRAS mutation." (PMID 35055084, 2022). "NRAS gene mutations were found to be associated with aggressive tumor features in many types of tumors, such as melanomas and colorectal cancer." (PMID 36051694, 2022). "ddPCR assays were performed to detect BRAF/NRAS mutations in plasma from 161 stage II/III melanoma patients enrolled in the AVAST-M adjuvant trial." (PMID 36579573, 2022). "Firstly, zinc finger and BTB domain containing 11 (ZBTB11) was identified as being hyper-edited in the NRAS mutation group, when compared to melanoma samples with BRAF or other mutations." (PMID 35993275, 2022). "NRAS mutations are detected in approximately 20% of treated melanomas, particularly those treated with BRAFi." (PMID 36286442, 2022). "A growing of literature has documented that the NRAS mutation is substantially related to a higher incidence of melanoma (i.e., 15–30% of melanoma), which is ten times higher than repeatedly than HRAS or KRAS." (PMID 36551688, 2022). "In contrast, no enrichment of any compound class showed selective toxicity in a melanoma line that developed BRAFi resistance through acquisition an NRAS mutation and lacks a de-differentiated phenotype." (PMID 35444937, 2022). "In melanoma, NRAS is the most common type of mutation in the RAS family, which is commonly seen in congenital pigmented nevi but rarely seen in dysplastic nevi." (PMID 35310910, 2022). "This study employed the CRISPR/Cas9 technology to generate three isogenic A375 melanoma cell lines with point mutations of NRAS Q61K, KRAS G13D and MEK1 Q56P, respectively." (PMID 36358868, 2022). "In conclusion, upon stepwise investigations of efficacy in increasingly sophisticated models, the antitumor peptide RDP22 was found to offer a new approach in the treatment of MUG-Mel2, an NRAS mutated melanoma with a high demand for curative treatment." (PMID 36428530, 2022). "Pimasertib, another MEK1/MEK2 inhibitor, has been compared with dacarbazine in a phase II trial in patients with untreated NRAS-mutated melanoma." (PMID 35053435, 2022). "The development of targeted therapies and immunotherapies has led to significant improvement in overall survival, particularly in non-NRAS-mutated melanoma (BRAF)." (PMID 36428530, 2022). "A number of studies have shown that NRAS-mutated melanoma requires the RAS/RAF/MEK/ERK and PI3K/Akt pathways to induce and maintain malignant phenotypes, and the growth of tumor can also be controlled through the interference of this pathway." (PMID 35310910, 2022). "The analyzed data suggested that the combination of the BRAF inhibitor encorafenib and the MEK inhibitor trametinib demonstrated the highest anti-tumor activity in both, BRAF- and NRAS-mutated melanoma." (PMID 36230853, 2022). "KRAS or HRAS mutations are detected infrequently in approximately 5% of melanoma patients, whereas NRAS mutations (NRASmut) are found in about 25% of patients, which makes NRAS the second most frequent mutation type after BRAF in melanoma." (PMID 36551302, 2022). "This was consistent with the fact that melanoma with BRAF or NRAS mutations were highly dependent on the MAPK pathway and showed a favorable response to MAPK inhibitors." (PMID 34718347, 2022). "Compared to superficial spreading subtypes of melanoma, lesions that were lentigo maligna melanoma (OR = 0.16, 95% CI 0.04–0.67) were at decreased odds of having an NRAS mutation (p = 0.02)." (PMID 35712493, 2022).